RBBP9 (RB binding protein 9, serine hydrolase)
Description:
Serine hydrolase (Probable). Catalyzes the hydrolytic activation of amino acid ester of the antiviral prodrug valacyclovir to its corresponding active drug, acyclovir. May negatively regulate basal or autocrine TGF-beta signaling by suppressing SMAD2-SMAD3 phosphorylation. May play a role in the transformation process due to its capacity to confer resistance to the growth-inhibitory effects of TGF-beta through interaction with RB1 and the subsequent displacement of E2F1.
Synonyms: BOG; RBBP10
Tractability: Small molecule: a structure with a bound ligand is known; it belongs to a druggable protein family. PROTAC: ubiquitination databases record sites on it; its protein half-life has been measured; a small molecule that binds it is known.
Target class: Enzyme; Hydrolase
Chemical probes: EMETINE, ML114
Gene: Protein-coding gene on chromosome 20 (18,486,540 to 18,497,234, reverse strand). Ensembl gene ENSG00000089050.
Subcellular location (Human Protein Atlas): Nucleoplasm
Gene Ontology:
Molecular function: protein binding; serine hydrolase activity; hydrolase activity
Biological process: xenobiotic metabolic process
Cellular component: nucleoplasm
Genetic constraint (gnomAD): Loss-of-function variants: 20 observed, 21.88 expected, observed/expected ratio (o/e) 0.91, 90% interval 0.64 to 1.33. The upper end of that interval is the gene's LOEUF score, 1.33, which puts it in group 5 of 6, group 1 being the genes least tolerant of losing a copy. Missense variants: 227 observed, 230.42 expected, observed/expected ratio (o/e) 0.99, 90% interval 0.88 to 1.1. Synonymous variants: 71 observed, 84.82 expected, observed/expected ratio (o/e) 0.84, 90% interval 0.69 to 1.02.
Homologues: Orthologues: chimpanzee RBBP9 (100% identical), macaque RBBP9 (99% identical), mouse Rbbp9 (91% identical), rabbit RBBP9 (90% identical), rat Rbbp9 (88% identical), guinea pig RBBP9 (88% identical), pig RBBP9 (80% identical), tropical clawed frog rbbp9 (73% identical), dog RBBP9 (70% identical), zebrafish rbbp9 (67% identical).
Diseases named in the same sentence as RBBP9 in open-access papers:
RBBP9 is named in the same sentence as 15 diseases in open-access papers, as found by Europe PMC text mining. Sharing a sentence is not in itself a finding about the gene and the disease. The quoted sentences say what the papers report.
pancreatic carcinoma (3 papers, 2020 to 2025). "Similarly, loss of RBBP9 SH activity has been shown to decrease proliferation in human pancreatic carcinoma cells." (PMID 33256189, 2020). "More recently, RBBP9 was identified as a metabolic serine hydrolase that promotes cancer cell survival by undermining the anti-proliferative function of TGF-β in a pancreatic cancer model." (PMID 39631567, 2025). "The serine hydrolase activity of RBBP9 was reported to suppress the TGF-β signaling pathway in pancreatic cancer cell lines." (PMID 39631567, 2025). "More recent studies have identified RBBP9 as a serine hydrolase that promotes cancer progression by inhibiting the anti-proliferative function of transforming growth factor (TGF)-b in a pancreatic cancer model." (PMID 39631567, 2025).
Fanconi anaemia (2 papers, 2023 to 2025). "Furthermore, a recent study using genome-wide small interfering RNA (siRNA) screening identified RBBP9 as a synthetic lethal gene essential for tumor cells deficient in Fanconi anemia (FA) proteins in a head-and-neck squamous cell carcinoma (HNSCC) model." (PMID 39631567, 2025). "A genome-wide siRNA screen on patient-derived Fanconi anemia pathway-deficient head-and-neck squamous-cell-carcinoma (HNSCC) cell lines identifies RBBP9 as a candidate therapeutic target." (PMID 36639418, 2023).
anemia (1 paper, 2012). A reduction in the number of red blood cells, the amount of hemoglobin, and/or the volume of packed red blood cells. "The panel included retinoblastoma binding protein 9 (RBBP9), Caspase recruitment domain family 11 (CARD11), Fanconi anemia complementation group c (FANCC), double minute 4 (MDM4), and breast cancer 1 (BRCA1)." (PMID 22859999, 2012).
breast carcinoma (1 paper, 2020). "Further investigation of RBBP9 SH activity in hPSCs might also provide a useful framework for understanding a wide variety of human cancers in which RBBP9 is expressed—including pancreatic, ovary, colon, lung, and breast cancer." (PMID 33256189, 2020).
colitis (1 paper, 2025). Inflammation of the colon. "The genetic inhibition of STAT1 or treatment with the JAK/STAT inhibitor reversed epithelial cell apoptosis and mitigated the enhanced susceptibility to DSS-induced colitis in Rbbp9-/- mice." (PMID 39631567, 2025). "To investigate whether RBBP9 deficiency sensitizes mice to colitis, we compared Rbbp9-/- and control wild-type (WT) mice administered either normal water or DSS." (PMID 39631567, 2025). "IL33-deficient mice are susceptible to DSS-induced colitis, similar to Rbbp9-/- mice." (PMID 39631567, 2025). "Finally, we examined whether UPA treatment effectively attenuated the susceptibility of Rbbp9-/- mice to DSS-induced colitis." (PMID 39631567, 2025). "The loss of RBBP9 enhanced the activation of interferon (IFN)/JAK/STAT1 signaling, resulting in susceptibility to DSS-induced colitis and AOM/DSS-induced CAC tumors by increasing epithelial cell apoptosis and immune activation." (PMID 39631567, 2025). "Furthermore, the increased pathological severity of colitis and CD45+ leukocyte infiltration in DSS-treated Rbbp9-/- mice was completely abolished by the simultaneous loss of STAT1 in Rbbp9-/-;Stat1-/- mice." (PMID 39631567, 2025). "Furthermore, the shortened colon length of DSS-treated Rbbp9-/- mice reverted to levels similar to the WT control, concomitant with the amelioration of histological colitis in DSS-treated Rbbp9-/- mice upon UPA treatment." (PMID 39631567, 2025). "Consequently, genetic inhibition of STAT1 or the use of the JAK/STAT inhibitor upadacitinib (UPA) reversed the apoptotic phenotype of Rbbp9-/- organoids and mitigated the enhanced colitis observed in dextran sodium sulfate (DSS)-treated Rbbp9-/- mice." (PMID 39631567, 2025). "We did not observe changes in IL33 levels in the colitis of RBBP9-deficient intestines." (PMID 39631567, 2025). "Given the critical role of RBBP9 in directly suppressing the phosphorylation of STAT1, we examined whether the loss of STAT1 reversed the apoptotic phenotype of epithelial cells and rescued the increased susceptibility of Rbbp9-/- mice to experimental colitis." (PMID 39631567, 2025). "Furthermore, the addition of recombinant IL33 did not cause any change in DSS-induced colitis in Rbbp9-/- mice." (PMID 39631567, 2025). "We established dextran sodium sulfate (DSS)-induced colitis, azoxymethane (AOM)/DSS-induced CAC model, and ApcMin/+ sporadic tumor model using wild-type and Rbbp9-/- mice." (PMID 39631567, 2025).
Colon Tumors (1 paper, 2025). "Consistent with the small intestinal tumors, the number of colon tumors was lower in ApcMin/+;Rbbp9-/- mice than in control mice." (PMID 39631567, 2025). "Consistent with a previous report demonstrating that the addition of inflammatory stimuli enhances tumor development in an ApcMin/+ mouse model, the number of colon tumors increased in both ApcMin/+ and ApcMin/+;Rbbp9-/- mice." (PMID 39631567, 2025). "Consequently, the addition of inflammatory stimuli enhanced colon tumor development more in ApcMin/+;Rbbp9-/- mice than in ApcMin/+ mice, accompanied by the presence of stronger inflammation-mediated proliferative activity." (PMID 39631567, 2025). "Importantly, DSS-treated ApcMin/+;Rbbp9-/- mice exhibited a significantly higher number of colon tumors than identically treated ApcMin/+ mice, accompanied by increased Ki67 and pS6 staining, indicating stronger inflammation-mediated proliferative activity." (PMID 39631567, 2025). "Notably, AOM/DSS-treated Rbbp9-/- mice developed more colonic tumors accompanied by an invasive carcinoma area than identically treated control mice." (PMID 39631567, 2025). "To test this hypothesis, we treated ApcMin/+;Rbbp9-/- mice with DSS and compared the number of colon tumors between ApcMin/+ and ApcMin/+;Rbbp9-/- mice, as DSS-induced inflammation mainly affects the colon." (PMID 39631567, 2025).
intestinal cancer (1 paper, 2025). "As inflammation is a widely recognized promoter of intestinal tumorigenesis, we examined whether the loss of RBBP9 could contribute to intestinal cancer in mice." (PMID 39631567, 2025).
intestinal tumors (1 paper, 2025). "In contrast, the ApcMin/+ mouse model, in which the development of intestinal tumors depends primarily on genetic alterations in epithelial cells rather than inflammation, showed the impaired occurrence and growth of intestinal tumors due to the loss of RBBP9." (PMID 39631567, 2025).
ulcerative colitis (1 paper, 2025). An inflammatory bowel disease involving the mucosal surface of the large intestine and rectum. "However, the functional role of RBBP9 in ulcerative colitis (UC) and colitis-associated cancer (CAC) remains elusive." (PMID 39631567, 2025).
tumor (7 papers, 2012 to 2025). "To determine the mechanism underlying the pro-tumor phenotype of Rbbp9-/- mice in the CAC model, we conducted an unbiased transcriptomic analysis (RNA sequencing [RNA-seq]) of tumors from AOM/DSS-treated Rbbp9-/- mice." (PMID 39631567, 2025). "Further, previous studies have reported retinoblastoma binding protein 9 (RBBP9) is a tumor-associated protein in pancreatic neoplasia, affecting cell cycle control and contributing to the TGF-β signaling pathway." (PMID 31057604, 2019). "The RBBP9 gene encodes a protein that is involved in the complex that binds to retinoblastoma (RB) tumor suppressor and regulates its activity as a monitor of apoptosis." (PMID 22859999, 2012). "Signal transducer and activator of transcription 1 inhibition or upadacitinib treatment mitigates inflammation and tumor development in Rbbp9-/- mice." (PMID 39631567, 2025). "This is consistent with previous reports demonstrating the pro-tumor function of RBBP9 by inhibiting the cell cycle regulatory protein RB or suppressing the TGF-β pathway mediated by its serine hydrolase activity." (PMID 39631567, 2025). "Previous reports in other cancer models have demonstrated the pro-tumor function of RBBP9 through either the inhibition of the cell cycle regulatory protein RB or the serine hydrolase activity-mediated suppression of the TGF-β pathway." (PMID 39631567, 2025). "RBBP9 can suppress the TGF-β signaling required for a concomitant decrease in the integrity of tumor cell-cell junctions, indicating its protective role for body health." (PMID 36032143, 2022). "Future work should aim to identify the C-terminal portion of RBBP9 substrates and understand how the hydrolase activity we have discovered relates to tumour cell proliferation." (PMID 35173328, 2022). "To determine the signaling pathways through which RBBP9 loss enhances intestinal inflammation and inflammation-mediated proliferation, we focused on the overlapping gene signatures between the RNA-seq data from the AOM/DSS and ApcMin/+ tumor models." (PMID 39631567, 2025). "Importantly both RBBP9-silencing as well as Emetine spared non-tumour FA cells." (PMID 36639418, 2023). "Similarly, both RBBP9-suppressed IECs (MODE-K) and ApcMin/+;Rbbp9-/- tumor organoids showed increased pSTAT1 levels when treated with IFN-γ compared with the respective controls with normal RBBP9 expression." (PMID 39631567, 2025).
cancer (3 papers, 2020 to 2025). A tumor composed of atypical neoplastic, often pleomorphic cells that invade other tissues. "Overexpression of the catalytically inactive mutant RBBP9-S75A in human carcinoma cells demonstrated that loss of RBBP9 SH activity resulted in decreased proliferation." (PMID 33256189, 2020). "These pioneering studies elucidated the crucial role of RBBP9 in cancer development, primarily using in vitro biochemical approaches." (PMID 39631567, 2025). "Although RBBP9 is expressed in various human cancer cells, its role in cancer development remains poorly understood." (PMID 39631567, 2025). "In this study, we investigated the critical role of RBBP9 in the development of intestinal inflammation and cancer using knockout mouse models and human bioinformatics analyses." (PMID 39631567, 2025). "Further investigation and clarification of RBBP9 and its activities will enable a greater understanding of its role in the maintenance of hPSCs, in development, and in the progression of cancer." (PMID 33256189, 2020). "Although accumulating evidence has revealed the importance of RBBP9 in physiological and pathological states, including inflammatory diseases, no previous studies have explored the role of RBBP9 in the development of intestinal inflammation and cancer." (PMID 39631567, 2025). "However, little is known of the roles RBBP9 plays either in normal development or cancer progression." (PMID 33256189, 2020). "For example, increased knowledge of the cell cycle, self-renewal and differentiation networks regulated by RBBP9 SH activity could provide useful insights into the role of RBBP9 in cancer cells, including slowly proliferating cancer cells resistant to current immunotherapies." (PMID 33256189, 2020). "More detailed analysis of the role of RBBP9 in hPSC maintenance and early development could provide useful information on how pluripotent cells are generated or maintained, and on mechanisms of both normal and cancer development." (PMID 33256189, 2020). "In addition, prior to this paper, no previous study has explored the role of RBBP9 in intestinal inflammation and cancer." (PMID 39631567, 2025).
RBBP9 also shares sentences with these, for which no sentence is quoted: colon cancer (1 paper); head and neck squamous cell carcinoma (1); invasive carcinoma (1); small intestinal tumors (1).